TNF (tumor necrosis factor)
Diseases named in the same sentence as TNF in open-access papers (continued):
Sharing a sentence is not in itself a finding about the gene and the disease.
psoriasis (continued). "TNF-α and IFN-γ are involved in inflammation and epidermal hyperplasia in psoriasis." (PMID 32632545, 2020). "Furthermore, higher concentrations of TNFα and IL6 in the serum of obese patients with psoriasis are believed to be significant markers of psoriasis." (PMID 32443588, 2020). "Paradoxical psoriasis (PP) may occur during treatment with anti-tumor necrosis factor-alpha (TNF-α) drugs in various chronic immune-mediated diseases, mainly inflammatory bowel diseases (IBD) and psoriasis." (PMID 33114187, 2020). "It has been widely used in patients with rheumatoid arthritis and psoriasis, significantly reducing serum levels of IL‐6, TNF‐α and IFN‐γ.9, 10 In a phase III clinical trial in patients with moderate‐to‐severe psoriasis conducted in India, itolizumab was effective and well tolerated." (PMID 33304584, 2020). "In psoriasis, keratinocytes play an important role in inflammatory mechanisms in the skin by producing cytokines-TNF, interferons, IL-17, and IL-20 members, which further leads to the generation of pro-inflammatory cytokines such as IL-1, IL-6, and TNF-α." (PMID 32181090, 2020). "In addition, TNF-α, CXCL1, IL-1β, IL-17A, and IL-36γ mRNA expression levels in IMQ-induced psoriasis-like lesions were significantly reduced by Cl-amidine administration compared to those in vehicle-treated Il36rn−/− mice." (PMID 33214582, 2020). "In the presented study, we evaluated the concentrations of TNF-α, IL-2, INF-γ, IL-10, and selected nitrosative stress parameters (NO, peroxynitrite, S-nitrosothiols, and nitrotyrosine) in NWS and SWS, as well as the plasma of psoriasis patients." (PMID 32164227, 2020). "Since both IFNγ+ and degranulating skin trNK cells produce TNFα, it is possible that skin NK cells participate in the progression of psoriasis by the production of TNFα rather than IFNγ." (PMID 32153574, 2020). "hBD is induced by TNF-α and IFN-γ, which are highly expressed in psoriasis lesional skin." (PMID 32947991, 2020). "In this study, we investigated the expression pattern and therapeutic effect of ghrelin in both contact dermatitis and psoriasis mouse models induced by oxazolone (OXA) and imiquimod (IMQ), respectively, and in TNF-α-stimulated RAW264.7 macrophages, NHEKs and skin fibroblasts." (PMID 30718736, 2019). "Some studies have shown decreased levels of IL-17A, TNF-α, S100A15, S100A7, S100A9 and IL-6 gene expression in PBMCs after NB-UVB treatment in patients with psoriasis whereas other pro-inflammatory mediators such as sVCAM-1, sICAM-1, sE-selectin, MMP-9, and MPO showed no significant reduction." (PMID 30865695, 2019). "Furthermore, slan+ monocytes, which are important pro-inflammatory cells found in psoriasis skin lesions, respond to LL37–RNA activation by secreting high amounts of TNF-α, IL-12, and IL-23." (PMID 30909615, 2019). "The benefit was seen regardless of previous exposure to TNF inhibitors, and there was only modest impact on psoriasis lesions." (PMID 31583079, 2019). "Blocking the TNF-α signaling pathway improves the inflammatory cycle of psoriasis, while it does not improve insulin sensitivity in patients with type 2 DM." (PMID 31491865, 2019). "While its efficacy for arthritis is not quite as high as that of the anti-TNF agents, it works very well for psoriasis." (PMID 31583079, 2019). "Recently, it has been demonstrated in a mouse line with inducible transgenic overexpression of human TNF, that macrophages, even in the absence of T and B cells, are sufficient for inducing psoriasis and are counter-regulated by Treg." (PMID 31357710, 2019). "Psoriasis is a Th1 and Th17 cell-mediated disease, and the presence of CD4+ Th1 cells is increased in lesional plaques, as well as the levels of cytokines consistent with the Th1 profile, such as IFN-γ and TNF-α." (PMID 30987186, 2019). "Angiogenesis – a marker of psoriasis pathogenesis – could also be promoted by angiogenic mediators like VEGF, TNF-α, IL-8, and IL-17." (PMID 31495284, 2019).
psoriasis (continued). "Several classes of biologicals have been developed against inflammatory cytokines, including TNF-α, IL-22, IL-23, and IL-17, although they are not effective in all individuals with psoriasis." (PMID 31252620, 2019). "Psoriasis patients were grouped as follows: patients without any therapy, patients treated with methotrexate, and patients treated with anti-TNF." (PMID 31101850, 2019). "Paradoxical psoriasis is suggested to be a side effect of all TNF antagonists, irrespective of the type and dosage, and usually disappears upon discontinuation." (PMID 31295952, 2019). "The datasets on psoriasis contain expression data on biopsy samples from lesional skin before, during, and after treatment with a biologic agent targeting TNF-α, as well as samples from non-lesional skin at baseline." (PMID 31420038, 2019). "In addition, TNF- α, IL-1β, IL-6, and INF-γ have been found to increase the production of C3 from the liver and probably from adipose tissue in psoriasis patients." (PMID 29416693, 2018). "Because anti-TNF treatment in wild-type mice increases pDC accumulation and type I IFN production in the skin, we determined whether it also induced a psoriasis-like phenotype." (PMID 29295985, 2018). "Recently, we could confirm that TNF controls the production of type I-IFN by pDCs and that anti-TNF induces its unabated overexpression driving paradoxical psoriasis." (PMID 30555460, 2018). "In line with this, there are no relapses of paradoxical psoriasis upon discontinuation of anti-TNF therapy, which supports lack of T-cell mediated disease memory in paradoxical psoriasis." (PMID 30555460, 2018). "Other psoriasis relevant mediators such as IL-17, TNFα, and IL-1 did not induce a significant increase in IL-23 secretion, regardless of IFNγ priming." (PMID 29535706, 2018). "The present meta-analysis found that TNF-α, IFN-γ, sE-selectin, IL-2, IL-6, IL-8, IL-18, IL-22, fibrinogen and C3 were elevated in serum of patients with psoriasis, indicating that serum levels of these cytokines may correlate to their levels in tissue." (PMID 29416693, 2018). "More than 10 years ago, elegant studies from the Griffith laboratory identified migrational impairment in LCs in response to IL-1β and TNF injection in non-lesional psoriasis skin." (PMID 29520279, 2018). "Psoriasis is primarily characterized as a Th1-driven disease because the levels of Th1 cytokines, such as IFN-γ, TNF-α, and interleukin (IL)-12, are markedly elevated in psoriatic lesions, while there is no such an increase in expression of Th2 cytokines (IL-4, IL-5, and IL-13)." (PMID 29899748, 2018). "As expected, the majority of CD3+CD8− T cells produced TNFα and IL-2; there was no reduction in TNFα with either carnosol or curcumin treatment, and only a small reduction in IL-2 production was seen in curcumin treated psoriasis PBMC." (PMID 29980703, 2018). "In addition to this axis representing the core of psoriasis pathogenesis, upstream cytokines (IFN-α, IFNγ, and TNFα), synergizing cytokines (IL-22 and TNFα), and downstream mediators (IL-8, IL1F9, and CCL20) complete the pathogenic puzzle." (PMID 29316717, 2018). "During the chronic phase of psoriasis, expansion and activation of T and DC subpopulations in lesional areas establishes a definite cytokine micromilieu, mostly represented by IFN-γ, IL-17, TNF-α, and IL-22." (PMID 30034395, 2018). "Though, a bi-specific dual variable domain immunoglobulin targeting both cytokines did not demonstrate increased efficacy compared to anti-TNF in RA, this remains to be tested in psoriasis." (PMID 30555460, 2018). "We could observe a significant titer of anti-TNFα and IFN-α in patients with psoriasis compared to healthy subjects and patients with atopic dermatitis." (PMID 29651292, 2018).
psoriasis (continued). "As one of the most important cytokines in psoriasis, IL-17A increases IL-8 and MCP-1 production in a dose-dependent manner in human dermal fibroblasts (HDFs) both at protein and mRNA levels, and there exists synergistic activity between IL-17A and TNF-α." (PMID 28217129, 2017). "We determined mRNA expression of the IFN-γ is elevated in lesional psoriasis skin compared to non-lesional and healthy skin, whereas TNF-α is elevated in atherosclerotic lesions relative to healthy coronaries." (PMID 29062018, 2017). "Currently available evidence on anti-TNFα therapy with MTX in psoriasis is limited to two randomized controlled trials (RCTs) on etanercept with MTX and a few observational studies and case series on other different anti-TNFα agents with MTX." (PMID 28148280, 2017). "Although the etiology of psoriasis has not yet been fully elucidated, the abnormal production of several inflammatory mediators from immune cells such as TNF-α, IL-6, IL-17, IL-22 and IL-23 are confirmed to play a key role in psoriasis." (PMID 29272319, 2017). "The introduction of anti-tumor necrosis factor medications has revolutionized the treatment of psoriasis with achievement of treatment goals (Psoriasis Area and Severity Index score 75, remission) that are not usually met with conventional systemics." (PMID 28148280, 2017). "Furthermore, the TNF- α treatment exhibited enhancement effect on mRNA expression of CCL17, CCL22 in HUVECs, which was similar to psoriasis sera." (PMID 29066845, 2017). "3D skin equivalents made of GATA3 shRNA transduced cells showed the tendency to express less FLG when compared to the respective control 3D skin equivalent under all investigated conditions (ns, AD-like (IL-4 and IL-13), and psoriasis-like (IL-22, OSM, IL-17, and TNFα) conditions)." (PMID 28928464, 2017). "Dexamethasone, which has been commonly used for atopic treatment of psoriasis and dermatitis and here was used as positive control, it also showed significantly lowering effects for the mRNA levels of IL-8, IL-23, and ICAM-1, except for TNF-α." (PMID 28464025, 2017). "In the context of psoriasis CAP has been shown to induce downregulation of IL-12 and upregulation of IL-1β, IL-6, IL-8, IL-10, tumor necrosis factor α (TNF-α), interferon gamma (IFN-γ), and vascular endothelial growth factor (VEGF) mRNAs in human keratinocytes." (PMID 28925941, 2017). "HaCaT cells were activated with TNF-α and IFN-γ, which are involved in the pathogenesis of psoriasis, and the gene expression of IL-6, which participated in the Th17 cell differentiation and psoriasis, was measured by real-time PCR." (PMID 29138509, 2017). "Psoriasis patient with MS showed higher level of many inflammatory cytokines in serum, such as CRP, TNF-α, IL-17, which may exacerbate the cutaneous inflammatory state so as to promote the progression of psoriasis." (PMID 29390261, 2017). "1,25(OH)D, 1,25-hydroxyvitamin D or calcitriol; 25OHD, 25-hydroxyvitamin D; BMI, body mass index; CRP, C -reactive protein; IL, interleukin; MetS, metabolic disease; PASI, psoriasis area and severity index; RDAs, recommended dietary allowances; TNF, tumor necrosis factor; VDR, vitamin D receptor." (PMID 28176237, 2017). "Another issue to be studied is the exact mechanism that causes the development of paradoxical psoriasis in patients without prior history of psoriasis who receive TNF antagonists for the treatment of inflammatory colitis or rheumatoid arthritis." (PMID 27158469, 2016). "As Aggawal and co-workers point out, its TNF-α inhibition alone justifies the cost of this development, since current TNF-α inhibitors are used not only for IBD, but also for osteoarthritis, psoriasis, and ankylosis, at a cost of $15,000–$20,000 per person per year." (PMID 27775675, 2016).
psoriasis (continued). "Current evidence suggests that psoriasis is a T-cell-mediated disease driven at least in part by a positive feedback loop from activated T-cells to antigen-presenting cells (APCs) that is mediated by IFN-γ, IL-1, and tumor necrosis factor-α (TNF-α)." (PMID 27274756, 2016). "In patients with psoriasis, a large proportion starts treatment withanti-TNF-α with high BMI, without compensation, because TNF does notinduce in these patients a "psoriatic cachexia"." (PMID 28099601, 2016). "In vitro results showed that several psoriasis-related cytokines, including IFN-γ, TNF-α, IL-17 and IL-22, could up-regulate IFI16 expression in keratinocytes via activation of STAT3 signaling." (PMID 27137868, 2016). "Various treatments that improve the symptoms of psoriasis, including epigallocatechin-3-gallate (EGCG), IL-12/23 and TNF-α inhibitors, could also suppress the expression or activity of NF-κB." (PMID 27708240, 2016). "In addition, psoriasis-related cytokines, including IFN-γ, TNF-α, IL-17 and IL-22, induced IFI16 up-regulation in keratinocytes via activation of STAT3 signaling." (PMID 27137868, 2016). "While the downstream effects on TNF-α and IL-10 have already been indicated as key components of this pathway, there also appears to be a role for fibroblast growth factor 10 (FGF10) in determining the influence of the SNS on psoriasis." (PMID 26550011, 2015). "The observation that circulating S1P levels were not corrected by anti-TNF-α treatment despite improvements in the skin further supports the rationale of targeting S1P receptors as an alternative therapy for severe psoriasis." (PMID 26174087, 2015). "In the viability and proliferation assay of cells that were treated with CKLF1-derived peptides, only TNF-α but not psoriatic sera was applied to culture media because the former provided psoriasis-like inflammation of relatively higher simplicity." (PMID 25915746, 2015). "It should be noted that for their original—and primarily tested—purpose, namely treating psoriasis, the TNF-α blocker did not come up to the expectations set." (PMID 26690116, 2015). "We found significant results in rs361525 (TNF-α) when we compared patients with type I psoriasis and patients with type II psoriasis, although we found no gender differences." (PMID 26613086, 2015). "In the psoriasis lesions, the production of IL23 bydendritic cells and keratinocytes is increased, stimulating Th17 cells withinthe dermis to produce "Th17 cytokines", which includes IL-17A, IL-17F,TNF-alpha, IL-21, and IL-22." (PMID 26734868, 2015). "These alterations were not reversed in severe patients (n = 16) after anti-TNF-α treatment despite significant improvement in psoriasis lesions." (PMID 26174087, 2015). "The fact that shifts in S1P levels were not ameliorated by anti-TNF-α treatment, despite improvements in the skin lesions, further supports targeting S1P receptors as therapy for severe psoriasis." (PMID 26174087, 2015). "Therefore, we performed a meta–analysis of randomized clinical trials (RCTs) to provide an up–to–date and comprehensive picture of the clinical efficacy of anti–TNF therapy for the most common EAMs in patients with AS—uveitis, IBD and psoriasis." (PMID 25888248, 2015). "The inflammatory DC subset found in AD is quite distinct from psoriasis without iNOS signature or high TNF production." (PMID 26229971, 2015). "While TNFα antagonist therapy is used for autoimmune or chronic inflammatory diseases, such as inflammatory bowel disease (IBD), numerous studies have reported new-onset psoriasis and lichen planus following such therapy." (PMID 24802997, 2014). "IL-6 was secreted at low levels with slightly more in psoriasis plaque T cells (0.09 versus 0.05 ng/ml, p = 0.18), while the soluble IL-1 receptor α (0.36 in ACD versus 0.28 ng/ml in psoriasis, p = 0.18) and TNF-α (4.5 versus 0.3 ng/ml, p = 0.18) were secreted in higher amounts by ACD T cells." (PMID 25058585, 2014).
psoriasis (continued). "Specifically, glutamine consumption enhances the production of many cytokines, and among them, tumor necrosis factor-α (TNF-α), interferon-γ (IFN-γ), interleukin-1β (IL-1β), and interleukin-6 (IL-6), all of which play an important role in psoriasis innate immunity." (PMID 25580230, 2014). "Interestingly, TNFα was also found to inhibit the expression of FLG and LOR by keratinocytes, and treatment of psoriatic patients with TNFα antagonists restored normal expression of FLG and LOR, in correlation with changes in psoriasis area and severity index." (PMID 25010647, 2014). "A clear increased concentration of IL-1α, TNF-α and IL-6 was found in skin lavage from lesion sites of psoriasis patients, in comparison with skin lavage from non-lesional sites, or from skin of healthy individuals." (PMID 25785188, 2014). "Psoriasis is characterized by the overproduction of interferon gamma (INF-γ), TNF-α, and IL-17." (PMID 24949467, 2014). "We found that incubation of 3D keratinocytes for 24 h with clinically relevant concentrations of infliximab, similar to those used in the treatment of psoriasis, suppressed the expression of IL-8, but not TNF-α, mRNA induced by PaCDase." (PMID 24586752, 2014). "We also assessed functionality of the T cells by evaluating the secretion of several inflammatory cytokines (IL-17A, IFN-gamma, IL-2, IL-33, TNF-alpha, IL-21, IL-22, and IL-27), from cell-sorted purified CD4+ and CD8+ T cells isolated from lesional and unaffected skin biopsies of psoriasis patients." (PMID 23468834, 2013). "In follow-up studies, the epidermal regulation of PRL and/or PRLR protein expression by TNF deserves to be characterized, since increased TNFα and PRL levels in psoriasis may both result in a decrease in PRLR expression." (PMID 23626671, 2013). "Some proteins which are published as important factors in pathogenesis were absent from DEGs in our microarray-meta analysis, such as TNF alpha, which is an important target in psoriasis therapy." (PMID 24303025, 2013). "The p-38 protein has awakened great interest as a potential molecular target for the treatment of psoriasis because the p38-MAPK plays a key role in the biosynthesis of many inflammatory cytokines such as TNF-α, and the expression of p38-MAPK is overregulated in psoriasis lesions." (PMID 23935446, 2013). "The Production of Nitric Oxide and Reactive Oxygen Species in Macrophages pathway was also significant, which is relevant since there is an abundance of TNF- and iNOS-producing dendritic cells (TIP-DCs), also called inflammatory myeloid DCs, present in psoriasis lesions." (PMID 22957057, 2012). "In α2/β1 integrin double-transgenic mice, skin irritation led to a chronic condition resembling psoriasis with persistent hyperplasia, cutaneous influx of CD4+ and CD8+ T-lymphocytes and secretion of pro-inflammatory cytokines like TNF-α, IFN-γ, IL-1β and IL-6." (PMID 22590584, 2012). "A French report showed that, in a mixed population of patients treated with TNF-α blockers, including psoriasis, 45 cases were collected of non-TB opportunistic infections (OIs)." (PMID 22645622, 2012). "The appearance of ANA is not a reason for stopping TNFα inhibitors in asymptomatic patients with psoriasis." (PMID 22937775, 2012). "miR-125b can also be defined as immuno-suppressive since it targets TNFα, but down-regulation of miR-125b in psoriasis is not a protective response, like up-regulation of miR-146, but rather a permissive response." (PMID 20594301, 2010). "TNFα mRNA is the most studied target of TTP, but a series of other cytokines, including IL-6, IL-10, IL-12, and granulocyte-macrophage colony stimulating factor (GM-CSF) are potential targets with a role in psoriasis pathogenesis." (PMID 20594301, 2010).